GAL (galanin and GMAP prepropeptide)
Diseases named in the same sentence as GAL in open-access papers (continued):
Sharing a sentence is not in itself a finding about the gene and the disease.
multiple sclerosis (2 papers, 2021 to 2022). A progressive autoimmune disorder affecting the central nervous system resulting in demyelination. "GAL2R mediated the neuroprotective effect promoted by GAL after injury and also activated PKC, PLC and ERK via Gq/11; this means that after binding to GAL2R, GAL agonists could be used to treat neurodegenerative diseases (e.g., multiple sclerosis)." (PMID 35954419, 2022).
ovarian carcinoma (2 papers, 2024 to 2025). A malignant neoplasm originating from the surface ovarian epithelium. "Secondly, the top six genes, each with more than 100 publications (KIT, EGF, STAR, GAL, FGF2, VIP), have known established roles in ovarian cancer." (PMID 40699804, 2025).
Parkinson’s (2 papers, 2020 to 2024). "It is well known that GAL plays a trophic role in the nervous system and protects neurons during neurodegenerative diseases such as Alzheimer’s and Parkinson’s." (PMID 39000048, 2024). "It is public knowledge that GAL plays trophic roles in the nervous system and protects neurons during neurodegenerative diseases like Alzheimer’s and Parkinson’s diseases." (PMID 33419365, 2020).
phaeochromocytomas (2 papers, 2022). "A high GAL2R mRNA expression was observed in human phaeochromocytomas and GAL inhibited the proliferation of phaeochromocytoma tumor cells." (PMID 35954419, 2022). "GAL and GALRs have been observed in human phaeochromocytomas." (PMID 35954419, 2022).
anaplastic astrocytoma (1 paper, 2020). "Also, 86% of anaplastic astrocytomas (WHO grade III) contained focal GAL-immunoreactivity (<1–65% of tumor cells)." (PMID 32265844, 2020).
Anorexia (1 paper, 2014). Lack of desire to eat (loss of appetite). "A study investigated the changes in NPY and GAL peptides at simulated high altitude (HA) and their possible role in anorexia in male SD rats." (PMID 25197671, 2014).
anxiety disorder (1 paper, 2013). A category of psychiatric disorders which are characterized by anxious feelings or fear often accompanied by physical symptoms associated with anxiety. "The SNP (rs948854) we investigated in our approach is located in the GAL promoter region and has been repeatedly linked with symptom severity and hypothalamic-pituitary-adrenal-axis activity in female patients suffering from panic and other anxiety disorders." (PMID 24086514, 2013).
astrocytic tumor (1 paper, 2020). A glial tumor of the brain or spinal cord showing astrocytic differentiation. "GAL-immunoreactivity showed substantial differences between and within different subtypes of 37 astrocytic tumors (WHO grade I–IV)." (PMID 32265844, 2020). "Furthermore, in all astrocytic tumors, areas with diffuse GAL-staining were noticed." (PMID 32265844, 2020).
behavioral disorders (1 paper, 2025). "Regarding the induction or triggering of behavioral disorders, SCOP (Pa = 0.861) and rutin (Pa = 0.857) show the highest risk, followed by GAL and chlorogenic acid." (PMID 40430525, 2025).
Cognitive impairment (1 paper, 2024). Abnormal cognition is characterized by deficits in thinking, reasoning, or remembering. "On the other hand, upregulation of GAL in AD is considered detrimental, as it inhibits acetylcholine release from cholinergic neurons, leading to cognitive impairment resulting from cholinergic system dysfunction." (PMID 38203854, 2024).
diffuse astrocytoma (1 paper, 2020). A low-grade (WHO grade II) astrocytic neoplasm. "In 57% of diffuse astrocytomas (WHO grade II), focal GAL-immunoreactivity (2–40% of tumor cells) was detected." (PMID 32265844, 2020).
endometrial cancer (1 paper, 2005). Primary or metastatic malignant neoplasm involving the endometrium (mucous membrane that lines the endometrial cavity). "While ER α-GAL4 fusion protein (GAL-ER α AF-2) showed a ligand-dependent transactivation function in human HEC59 endometrial cancer cells, a transient coexpression of hMSH2 led to an approximately 2.5-fold increase in the luciferase activity compared to that of GAL-ER α AF-2 alone." (PMID 15886699, 2005).
enteritis (1 paper, 2021). Inflammation of the small intestine. "Meanwhile, GAL has been shown to be involved in the differentiation of mucosal-type mast cell (MMCs) in vivo, while In the same study, the authors suggest that GAL released from the submucosal neurons may contribute to the differentiation and proliferation of MMC during enteritis." (PMID 34769120, 2021).
esophageal cancer (1 paper, 2022). A primary or metastatic malignant neoplasm involving the esophagus. "Many nerve fibers containing GAL have been reported in cardiac and esophageal carcinomas; these fibers contacted closely with cancer cells, including those encircling tumor cells." (PMID 35954419, 2022).
galactosemia (1 paper, 2024). "A recent survey of the NBS knowledge among health professionals found that NBS for CH, CF, PKU, galactosemia (GAL), HGB, and SCID were available in certain locations and suggested an overall lack of awareness of NBS that needed to be addressed nationally." (PMID 38920845, 2024).
ganglioglioma (1 paper, 2020). A well differentiated, slow growing neuroepithelial neoplasm composed of neoplastic, mature ganglion cells and neoplastic glial cells. "IHC analysis of three gangliogliomas (WHO grade I) revealed focal (<1 and 6% of tumor cells) as well as diffuse GAL staining in two of the three cases." (PMID 32265844, 2020).
gastric adenocarcinoma (1 paper, 2020). "However, studies aimed at comparing the density of GAL-positive nerve fibers in the control group and in people with gastric adenocarcinoma revealed an increase in GAL-IR nerve fibers in a circular muscle layer and lamina muscularis mucosae in the disease group." (PMID 33552060, 2020).
gastroenteritis (1 paper, 2020). An inflammatory disorder that affects the upper and lower gastrointestinal tract. "Additionally, it is tempting to speculate that GAL may be used in the treatment of gastroenteritis." (PMID 33552060, 2020).
giant cell glioblastoma (1 paper, 2020). "In gliosarcoma (WHO grade IV), only half of the samples displayed focal GAL-immunoreactivity (15–70% of tumor cells), whereas all giant cell glioblastomas (WHO grade IV) revealed focal GAL-immunoreactivity (35–80% of tumor cells)." (PMID 32265844, 2020).
Headache (1 paper, 2022). Cephalgia, or pain sensed in various parts of the head, not confined to the area of distribution of any nerve. "In this study, GAL expression was investigated in the rat dura mater to demonstrate its possible function in headache using immunohistochemical techniques." (PMID 35338230, 2022). "However, similar to the human DRG, it is possible that GAL expression changes in the human TG during headache and that GAL contributes to nociceptive transmission from the human head." (PMID 35338230, 2022).
heroin addiction (1 paper, 2013). "The presented result may significantly contribute to current knowledge of the role of GAL in opioid addiction susceptibility, which so far was mainly based on one study that found a GAL variant located in intron 2 (rs694066) to be associated with heroin addiction." (PMID 24086514, 2013).
hyperlipidaemia (1 paper, 2014). "A previous study demonstrated an association in Dutch, Finnish, and Mexican familial combined hyperlipidaemia families with an allele residing 5.6 kb upstream of the transcriptional start site of the GAL gene." (PMID 25228436, 2014).
hyperprolactinemia (1 paper, 2022). Abnormally high level of prolactin in the blood. "In transgenic mice, the overexpression of GAL in these cells promoted the synthesis and release of prolactin favoring hyperprolactinemia; moreover, this study showed that pituitary GAL favored pituitary hyperplasia (especially lactotrophs) in an estrogen-dependent manner." (PMID 35954419, 2022).
Hypertension (1 paper, 2020). The presence of chronic increased pressure in the systemic arterial system. "Moreover, the adverse events such as dysrhythmias, agitation and seizures, observed with doxapram, were only observed with GAL‐053.24, 25, 26, 27 Phase 1 trials with GAL‐054 in healthy volunteers, however, found that GAL‐054 caused hypertension, as previously seen in rat models." (PMID 31423744, 2020).
Impaired glucose tolerance (1 paper, 2021). An abnormal resistance to glucose, i.e., a reduction in the ability to maintain glucose levels in the blood stream within normal limits following oral or intravenous administration of glucose. "Moreover, in patients with impaired glucose tolerance, a high level of GAL has been associated with hyperglycemia." (PMID 33802616, 2021). "One-two hours after food intake, the levels of GAL, glucose and insulin were higher in the former group than in controls and, in addition, body weight was higher in patients with impaired glucose tolerance." (PMID 33802616, 2021). "Serum levels of GAL, glucose and insulin have been measured in patients suffering from impaired glucose tolerance and in control subjects with normal glucose tolerance." (PMID 33802616, 2021).
insulinoma (1 paper, 2022). "In the RINm5F insulinoma cell line, GAL inhibited the activity of AC and moderately suppressed the accumulation of insulin, but did not affect cell proliferation; Gi3, a G protein coupled to GALRs, was involved in this inhibition." (PMID 35954419, 2022). "The expression of GAL1R has been demonstrated in insulinoma cells; however, the proliferative or antiproliferative actions mediated by GAL on these cells are currently unknown." (PMID 35954419, 2022). "GAL opened adenosine triphosphate (ATP)-sensitive K+ channels and hyperpolarized cell membranes in the rat RINm5F insulinoma cell line, and the peptide blocked the activity of AC and the secretion of insulin via the interaction with Gαi1, Gαi2 and Gαi3 proteins." (PMID 35954419, 2022).
intervertebral disc degeneration (1 paper, 2017). "Previous studies on intervertebral disc degeneration models have not addressed the expression of other sympathetic nervous system-related molecules, such as DBH, NPY, SOM, LENK, and GAL." (PMID 28762133, 2017).
ischemia (1 paper, 2022). A hypoperfusion of the BLOOD through an organ or tissue caused by a PATHOLOGIC CONSTRICTION or obstruction of its BLOOD VESSELS, or an absence of BLOOD CIRCULATION. "Next to the neuroprotective properties, especially visible during ischemia and neuro-degenerative processes, but also noted in gastrointestinal diseases, GAL regulates intestinal secretion, motility, blood flow, and immunological processes, and affects intestinal absorption." (PMID 36498260, 2022).
ischemic stroke (1 paper, 2017). A stroke disorder caused by obstruction of blood flow to the brain, due to thrombotic (local blood clot formation) or embolic (due to a blood clot or other material traveling from another site) event. "In fact, we also observed a significant improvement in neurological outcome after GAL post-treatment in ischemic stroke mice at 1-7 d." (PMID 28203483, 2017). "Here, we provided evidence for the first time that GAL can protect the mouse brain from ischemic stroke injury resulting not only in a reduced infarct size, but also alleviating neurological deficits." (PMID 28203483, 2017). "Meanwhile, after 24 h of reperfusion, both GAL and GalR1 showed a significant increase in the ipsilateral versus contralateral cortex, suggesting GAL’s involvement in ischemic stroke." (PMID 28203483, 2017). "Here, the models of 1 h middle cerebral artery occlusion (MCAO)/1-7 d reperfusion (R)-induced ischemic stroke and in vitro cell ischemia of 1 h oxygen-glucose deprivation (OGD)/24 h reoxygenation in primary cultured cortical neurons were used to explore GAL’s effects and its underlying mechanisms." (PMID 28203483, 2017). "In order to determine whether manipulating GalR2 expression levels in primary cultured neurons would affect GAL’s role in ischemic stroke, lentiviral knockdown of GalR2 in primary cultured neurons was utilized." (PMID 28203483, 2017). "However, the role of GAL in ischemic stroke is still unclear." (PMID 28203483, 2017). "In conclusion, we first provide evidence that GAL protein and mRNA show significant increases within 48 h of reperfusion after 1 h MCAO, establishing a possible connection between GAL and the mouse brain under ischemic stroke." (PMID 28203483, 2017).
lymph node metastasis (1 paper, 2020). "Because GAL inhibits cell proliferation, low GAL level may promote cancer growth and lymph node metastasis." (PMID 33552060, 2020).
migraine (1 paper, 2022). "However, the present co-expression data on GAL and CGRP in nerve fibers within the dura mater suggest that neural GAL is also associated with migraine." (PMID 35338230, 2022). "In addition, the proportion of sensory neurons expressing GAL mRNA decreases in the DRG of a patient with migraine-like pain, compared to the un-lesioned dorsal root ganglion." (PMID 35338230, 2022).
mononeuropathy (1 paper, 2014). Disease or trauma involving a single peripheral nerve in isolation, or out of proportion to evidence of diffuse peripheral nerve dysfunction. "A similar effect is observed in some pathological conditions, such as acute inflammation or mononeuropathy, where the microinjection of supraspinal exogenous GAL also decreases nociception." (PMID 25405608, 2014).
muscular dystrophy (1 paper, 2017). Muscular dystrophy (MD) refers to a group of more than 30 genetic diseases characterized by progressive weakness and degeneration of the skeletal muscles that control movement. "All muscular dystrophy hallmarks (degeneration/regeneration cycles, inflammatory response, fibrosis) were clearly visible in various 3-week-old dy3K/dy3K, dy3K/OPN and dy3K/GAL muscles, but not in osteopontin or galectin-3 knockout mice." (PMID 28281577, 2017).
myocardial infarction (1 paper, 2022). Gross necrosis of the myocardium, as a result of interruption of the blood supply to the area, as in coronary thrombosis. "In the animal model, GAL can limit myocardial infarction size, improve postischemic cardiac function recovery, and suppress myocardial apoptosis and mitochondrial oxidative stress in cardiac hypertrophic remodeling." (PMID 35453489, 2022).
oligoastrocytoma (1 paper, 2020). A WHO grade II tumor composed of a conspicuous mixture of two distinct neoplastic cell types morphologically resembling the tumor cells in oligodendroglioma and diffuse astrocytoma. "IHC analysis of one oligoastrocytoma (OA, NOS; WHO grade II) and one anaplastic oligoastrocytoma (OAA, NOS; WHO grade III) revealed focal (20 and 90% of tumor cells) as well as diffuse GAL staining." (PMID 32265844, 2020).
oligodendroglial tumor (1 paper, 2020). Oligodendrogliomas are cerebral tumors that are differentiated from other gliomas on the basis of their unique genetic characteristics and better response to chemotherapy. "IHC analysis of 15 human oligodendroglial tumors (WHO grades II and III) revealed focal and diffuse GAL-immunoreactivity in the majority of cases." (PMID 32265844, 2020).
oligodendroglioma (1 paper, 2020). A well-differentiated (WHO grade II), diffusely infiltrating neuroglial tumor, typically located in the cerebral hemispheres. "In more detail, 78% of oligodendrogliomas (WHO grade II) showed focal GAL-immunoreactivity (<1–10% of tumor cells) and 89% contained areas of diffuse GAL staining." (PMID 32265844, 2020).
oropharyngeal cancer (1 paper, 2018). Carcinoma, predominantly squamous cell, arising from the epithelial cells of the oropharynx. "Methylation of the GAL promoters was positively correlated with recurrence in patients with oropharyngeal cancers (OR = 3.006, 95% CI 1.134–7.968, P = 0.027)." (PMID 29682090, 2018).
osteosarcoma (1 paper, 2023). A usually aggressive malignant bone-forming mesenchymal neoplasm, predominantly affecting adolescents and young adults. "A risk model composing of ZYX, GJA5, GAL, GRAMD1B, and CKMT2 was established for assessing osteosarcoma prognosis." (PMID 38039294, 2023). "Considering the heterogeneity between molecular subtypes defined by specific oxidative stress genes, we identified the DEGs between the two molecular subtypes and deduced a risk assessment system composing of ZYX, GJA5, GAL, GRAMD1B, and CKMT2 for the prognosis of osteosarcoma." (PMID 38039294, 2023).
pancreatic cancer (1 paper, 2023). "Anti-GAL antibodies have been confirmed to play a role in the immunotherapy of pancreatic cancer." (PMID 37316840, 2023).
peripheral nerve injury (1 paper, 2019). Injury to a peripheral nerve. "Similarly to GAL, NPY is also involved in the modulation of neuropathic pain induced by peripheral nerve injury." (PMID 31023212, 2019).
pilocytic astrocytoma (1 paper, 2020). Pilocytic astrocytoma is a rare subtype of low-grade glioma of the central nervous system characterized by a well circumscribed, often cystic, brain tumor with a discrete mural nodule and long, hair-like projections that extend from the neoplastic astrocytes. "Sixty percent of pilocytic astrocytomas (WHO grade I) displayed focal GAL-immunoreactivity (<1–18% GAL-positive tumor cells)." (PMID 32265844, 2020).
pituitary tumor (1 paper, 2022). A benign or malignant neoplasm affecting the pituitary gland. "In fact, high estrogen levels promoted prolactin-secreting pituitary tumors, which in turn released GAL and, in estrogen-induced prolactinomas, the expression of the GAL gene and the level and secretion of GAL increased in the rat anterior pituitary." (PMID 35954419, 2022). "Thus, in the rat MtTW-10 pituitary tumor cell line, GAL mRNA levels highly increased after the administration of estradiol." (PMID 35954419, 2022). "Importantly, GAL/GALR expression is related to the pituitary tumor stage." (PMID 35954419, 2022). "In normal pituitaries, the co-existence of GAL and ACTH has been reported in corticotrophs and, in the same cells, GAL and ACTH were also co-expressed in nonfunctioning and functioning pituitary tumors." (PMID 35954419, 2022).
primary immunodeficiency (1 paper, 2024). "GAL and SGCA were associated with fatty acid metabolism in the GSE58095 dataset; GAL and SGCA were also enriched in the primary immunodeficiency and cytosolic DNA sensor in the GSE100927 dataset." (PMID 39050259, 2024).
psoriasis (1 paper, 2023). An autoimmune condition characterized by red, well-delineated plaques with silvery scales that are usually on the extensor surfaces and scalp. "Moreover, the lipid metabolism genes THRSP and GAL, which are expressed by keratinocytes and in eccrine sweat glands, have also been reported to be downregulated in uninvolved psoriasis skin." (PMID 37131254, 2023).
rectal cancer (1 paper, 2021). A primary or metastatic malignant neoplasm that affects the rectum. "Seven hub genes, including SAA1, AGT, GNG4, GAL, CXCL1, CXCL2, and CXCL3, were upregulated in rectal cancer tissues." (PMID 34269159, 2021). "Besides CXCL1, CXCL2, and CXCL3, we mined seven other hub genes related to rectal cancer, including SAA1, AGT, GNG4, SST, SSTR2, GAL, and CXCL12." (PMID 34269159, 2021).
renal carcinoma (1 paper, 2020). A carcinoma arising from the epithelium of the renal parenchyma or the renal pelvis. "Among these, increased expression of GAL has been reported to promote the migration of renal cancer cells, while its knockdown reduces cell migration and invasion." (PMID 33162809, 2020).
sarcoma (1 paper, 2023). A usually aggressive malignant neoplasm of the soft tissue or bone. "EWSR1-WT1-regulated genes expressed more highly in recurrent than primary DSRCT included GJB2, GAL, and GALP, which were recently identified as highly enriched in DSRCT compared to other sarcoma types." (PMID 37457440, 2023).